LAMP3 (lysosome associated membrane protein 3)
Diseases named in the same sentence as LAMP3 in open-access papers (continued):
Sharing a sentence is not in itself a finding about the gene and the disease.
systemic lupus erythematosus (1 paper, 2025). An autoimmune multi-organ disease typically associated with vasculopathy and autoantibody production. "The results showed that IFI27 and LAMP3 were mainly enriched in cell cycle, Systemic Lupus Erythematosus, cytosolic DNA sensing pathway, toll-like receptor (TLR) signaling pathway and nod-like receptor (NLR) signaling pathway." (PMID 40297850, 2025).
thyroid cancer (1 paper, 2024). "Then, we studied myeloid cells of thyroid cancer and obtained 6 subclusters: macrophages, monocytes, type 1 and type 2 conventional dendritic cells, plasmacytoid dendritic cells, and LAMP3-DCs." (PMID 38478516, 2024).
tumor (169 papers, 2008 to 2026). "To further validate the association between TLSs and LAMP3+ DCs, we retrospectively analyzed postoperative tumor samples from 40 patients with LARC using multiplex immunohistochemistry (IHC) and mIF." (PMID 41190765, 2026). "In bladder cancer, tumor-associated macrophages (TAMs) adopt a pro-tumor phenotype while dendritic cells differentiate into immunosuppressive LAMP3+ subsets." (PMID 41050070, 2025). "Consistent with previous findings, DC_LAMP3 is linked to tumor antigen presentation and has been shown to suppress DC function within the TME." (PMID 40725006, 2025). "In most tumours, both chemokines and chemokines receptors were heavily associated with LAMP3 in pan‐cancer except KICH." (PMID 38146591, 2024). "According to studies, LAMP3 is overexpressed in a variety of cancer types and is linked to tumor spread and a poor prognosis for patients." (PMID 38922530, 2024). "Our study indicated that LAMP3 was significantly associated with a stage in several tumours, which has a relationship with the prognosis of patients." (PMID 38146591, 2024). "As a result of these findings, it was concluded that LAMP3 was significantly associated with tumour progression, especially within the immune microenvironment." (PMID 38146591, 2024). "Studies have reported that LAMP3 is overexpressed in multiple cancer types and that it is associated with tumor metastasis and poor patient prognosis." (PMID 37062845, 2023). "Tumor-associated macrophages and LAMP3+ DCs are involved in mediating T cell activity and form intercellular interaction hubs with TASCs." (PMID 35999201, 2022). "Lysosome associated membrane protein-3 (LAMP3) represents another tumor promoting protein for which the greatest downregulation was observed during dual therapy (35.0%) compared to DPCP monotherapy (16.5%) or pembrolizumab monotherapy (2.1%)." (PMID 36572780, 2022). "Mature LAMP3+ DCs were also reported to exist in multiple tumor types and were associated with increasing tumor-infiltrating lymphocytes in the local tumor lesion." (PMID 35831283, 2022). "PERK-ATF4 arm directly upregulates vascular endothelial growth factor A (VEGFA) and Lysosomal-Associated Membrane Protein 3 (LAMP3) thereby regulating tumour vascularity and invasion." (PMID 29545931, 2018). "Accordingly, the activity of LAMP3 has been linked with tumor metastasis and poor prognosis independently of HIF-1." (PMID 30250843, 2018). "Chi-square analysis showed that the high LAMP3 expression was notably linked to the degree of tumor differentiation and advanced TNM stage." (PMID 28607528, 2017). "LAMP3 is a lysosomal membrane associated protein important in dendritic cells and potentially involved in tumor invasion, while ETV7 is a transcription factor associated to cell proliferation and tumorigenesis." (PMID 25401416, 2014). "Tumor-associated CD83 + CCR7 + LAMP3+ DCs were found to selectively express in tumor tissue." (PMID 39256364, 2024). "In 31 out of 39 tumours, LAMP3 has a sharp association with tumour purity." (PMID 38146591, 2024). "We also checked the potential origins of LAMP3+ DC in tumor and observed more cDC2-derived LAMP3+ DC, which could be associated with higher proportions of cDC2 in ascites." (PMID 37488416, 2023). "LAMP3+ DCs exhibit characteristics associated with both anti-tumor immunity and tolerance." (PMID 38012715, 2023). "DC maturation in the TME can be promoted by HMGB1 stimulated by preoperative chemoradiotherapy and is accompanied by surface molecule (CD80, CD86, CD208, and LAMP3) expression with anti-tumor functions of tumor-associated antigen presentation, which facilitates effective CD8+ T cell activation." (PMID 33995371, 2021).
tumor (continued). "In the multivariate analysis, high expression of LAMP3 (P = 0.048) was significantly linked to the poor overall survival, similarly as the degree of tumor differentiation (P = 0.020) and advanced TNM stage (P = 0.001) were always regarded as significant predictors of poor prognosis of OSCC patients." (PMID 28607528, 2017). "Because of the role of LAMP3 in tumor-associated hypoxia, future research is warranted to investigate whether LAMP3 plays a role in hypoxia-associated treatment failure and whether LAMP3 is a valid novel therapy target in gastrointestinal cancers." (PMID 25362357, 2014). "Lysosomal‐associated membrane protein 3 (LAMP3), is a member of the Lysosome Associated Membrane Proteins and is involved in the malignant phenotype such as tumour metastasis and drug resistance, while the mechanisms that regulate the malignant progression of tumour remain vague." (PMID 38146591, 2024). "In multivariate analysis, high LAMP3 expression remained significantly associated with poor overall survival (HR, 2.519, 95% CI, 1.062-5.980; P=0.036), as did tumor differentiation (HR, 4.741, 95% CI, 2.252-9.982; P<0.001) and tumor stage (HR, 1.988, 95% CI, 1.260-3.137; P=0.003)." (PMID 25362357, 2014). "Within the tumor microenvironment, we identified distinct subtypes including LAMP3 + dendritic cells and iCAF fibroblasts that followed unique pseudotime trajectories linked to progression." (PMID 41214597, 2025). "They found that CXCL13+PD-1+ CD4+ T cells (equal to CD4.c16/17) augmented antitumor cytotoxicity through interaction with LAMP3+ DCs in tumor-draining lymph nodes (TDLNs)." (PMID 38343549, 2024). "Among immunoinhibitors, PVRL2, CD160, KDR and VTCN1 were also negatively correlated with LAMP3 expression in many tumours." (PMID 38146591, 2024). "Its tumor-specific coincidence with the LAMP3+ DC suggests that mesenchymal-derived interferon is necessary to initiate the tumor interferon signaling for the subsequent recruitment of immune cells and T cell priming." (PMID 38744958, 2024). "Subsequently, we examined LAMP3 overexpression in tumour tissues from both TCGA data and clinical samples." (PMID 38217544, 2024). "There is a significant correlation between the expression of LAMP3 and PD‐L1.Our study elucidates that LAMP3 has different expression patterns and genetic alteration patterns in different tumours." (PMID 38146591, 2024). "The distribution of these clusters was generally stable across lesion stages, except for tumor-derived pDC_IRF7, DC3_LAMP3, and Mono_CD16 clusters." (PMID 38720887, 2024). "Higher numbers of CD4+ T cells, CD8+ T cells, CD20+ B cells, CD68+ macrophages, LAMP3+ DCs, PD-L1+ cells, and TLSs were detected in patients with a single tumor than in those with multiple tumors." (PMID 38254190, 2024). "Subsequently, we probed the level of LAMP3 expression in single tumor UCEC using the collected UCEC tissues and normal tissues from the TCGA database, which suggested an upregulation of LAMP3 expression in UCEC tissues." (PMID 38217544, 2024). "To clarify the underlying biological function of LAMP3 in tumours, we performed Kyoto Encyclopedia of Genes and Genomes (KEGG) by gene sets with a greater than 0.3 absolute value of correlation with LAMP3 in each tumour in the UALCAN database." (PMID 38146591, 2024). "Among immunostimulators, CD276, PVR, TNFRSF14, TNFRSF25 and TNFSF9 were also negatively correlated with LAMP3 expression in some tumours." (PMID 38146591, 2024). "Then, we further resolved LAMP3 expression in tumor and normal tissues utilizing RNA-seq data from the TIMER website, identifying that LAMP3 exhibited higher expression in 11 types of tumor tissues, including UCEC." (PMID 38217544, 2024).
tumor (continued). "An increasing number of reports confirm that RNA modifications have an essential modulatory role in tumor pathogenesis, which prompts us to study their link with LAMP3 in UCEC." (PMID 38217544, 2024). "Lamp3+ dendritic cells, known for their role in modulating tryptophan metabolism and exerting immunomodulatory effects, contribute to tumor escape and progression." (PMID 39493764, 2024). "Our results showed that the scores of OV and HNSC stages 1–4 were lower and lower, and the larger the stage, the lower the LAMP3 expression, elucidating that the higher the LAMP3 expression in the two tumours, the better the prognosis." (PMID 38146591, 2024). "With the CCLE database, we explored the expression distribution of LAMP3 in 32 tumor tissues, and the outcome implied that it possessed high expression in various tumor tissues such as SCLC, BLCA, ESCA, and UCEC." (PMID 38217544, 2024). "Leveraging the potent antigen-presenting capacity of LAMP3+ DC provides a pathway for developing cancer vaccines that target specific tumor antigens." (PMID 38649887, 2024). "Further investigation into the regulatory process of LAMP3+ DCs in tumors revealed that tumor-infiltrating LAMP3+ DCs have lower expression of IL15 compared to those in adjacent non-tumor tissue." (PMID 38552055, 2024). "To validate the expression of LAMP3 in human tumour tissues and its relationship with immune checkpoint proteins, we detected the correlation between LAMP3 and immune protein PD‐L1 in clinic samples by immunohistochemistry." (PMID 38146591, 2024). "In pan‐cancer, the correlation between LAMP3 and tumour‐infiltrating lymphocytes, immunostimulators, immune inhibitors and so on remains vague." (PMID 38146591, 2024). "RNA velocity analysis has demonstrated a directional flow of tumor-derived cells towards LAMP3+ DCs in LNs." (PMID 38012715, 2023). "For instance, the PDCD1‐PDCD1LG2 interaction between CD8+ Tex cells and LAMP3+ DCs, which mediates tumor immune escape, was prominent in ADC samples." (PMID 36725337, 2023). "Recurrent HCC tumor cells interact with cDC2/LAMP3+ DCs via CD274/CD80 and CTLA4/CD80, leading to the formation of clusters around DCs and subsequently reducing antigen presentation and T cell activation efficiency." (PMID 38012715, 2023). "Then, we detected the protein expression of LAMP3 in 18 pairs of fresh human CRC tissues (T) and matched adjacent normal tissues (N), and observed higher expression of LAMP3 in tumor tissues, similar to the expression trends for RPL21." (PMID 37062845, 2023). "PD-L1 expression is universally upregulated in tumor-derived LAMP3+ DCs across nearly all cancer types." (PMID 38012715, 2023). "We also assessed LAMP3 expression in tumor buds and found that it was positively correlated with tumor budding grade." (PMID 37062845, 2023). "Lastly, we analyzed the correlation between the scores of RPL21 and LAMP3 expression in tumor buds and observed a significant positive correlation." (PMID 37062845, 2023). "We further confirmed the strong correlation between PD-1-expressing T cells and PD-L1-expressing LAMP3+ DCs in HPSCC tumor tissues using FACS, providing further evidence for their interactions." (PMID 37853464, 2023). "A pan-cancer single-cell transcriptome analysis of myeloid cells confirmed that although the proportion of cDC2 was much higher in tumor tissues, cDC1-derived LAMP3+ cDCs were more abundant than cDC2-derived ones." (PMID 35831283, 2022). "The authors also confirmed a previously reported cDC subset, LAMP3+ cDCs, which widely exist across all 15 tumor types." (PMID 35504878, 2022). "TASCs, DC_LAMP3, and tumor cells, all highly expressed NECTIN2 and PVR (CD155), whose interaction with TIGIT blocks T-cell activation and proliferation." (PMID 35999201, 2022).
tumor (continued). "By ligand and receptor analysis, we observed TASCs, Mφ_APOE and LAMP3+ DCs, as the key mediators in complex intercellular networks of interaction, orchestrated the immunosuppressive microenvironment and promoted tumor progression." (PMID 35999201, 2022). "Flow cytometry analysis also demonstrated that the ratio of LAMP3+DCs in neoadjuvant MPR tumor lesions was significantly higher than that in treatment-naive tumor tissues, and displayed an increasing trend in MPR than non-MPR tumor tissues." (PMID 35831283, 2022). "Unlike the previous three classical DC subtypes which were shared by both tumor and normal samples, almost all cells in M06 were derived from tumor samples, suggesting that this LAMP3+ DC subsets were strongly enriched in tumor samples." (PMID 35664061, 2022). "Recently, there was a report showing that PD-L1 was universally upregulated in tumor-derived LAMP3+ conventional DCs in almost all human cancer types." (PMID 35917184, 2022). "Peripheral DCs infiltrate the tumor and are induced to differentiate into LAMP3+ DCs, which express PD-L1/PD-L2 interacting with PD-1 on CD8+ T cells and thus promote CD8+ T cell exhaustion." (PMID 35632758, 2022). "In contrast, increased BTG2 and LAMP3 expression are accompanied by increased sensitivity of tumor cells to chemotherapeutic agents, such as axitinib, oxaliplatin, and fluorouracil." (PMID 35372503, 2022). "LAMP3 was previously shown to mediate migration from tumor to regional lymph nodes and exert regulatory capacity on other cells." (PMID 34783307, 2021). "Five cell types, TIMP1+M3, S100A8+N3, TUBB+Mcyl, LAMP3+DC3, and TCL1A+pDC, all of which were enriched in MSC2, were positively associated with tumor progression (FDR < 0.05)." (PMID 34659209, 2021). "Among the four clusters of dendritic cells, DC_C2_CD1C, DC_C3_LAMP3, and DC_C4_JCHAIN were derived from tumours, and DC_C1_FCER1A was derived from peripheral blood, which was assigned as monocyte-like DC because of the expression of monocyte marker S100A8." (PMID 33531485, 2021). "To find new potential checkpoints, we investigated the cell-cell communications between tumor-promoting immune cells (CD4_CXCL13, CD4_FOXP3, CD8_CXCL13, CD8_ISG15, Mac_C1QA, Mac_ISG15, Mac_SPP1 and cDC3_LAMP3) and the ductal epithelial cells." (PMID 35087839, 2021). "The significantly higher DC densities were observed at the tumour’s invasive margin for LAMP3+, CD123+, CD83+ and DC-SIGN+ cells, in comparison with intratumoural area (p < 0.001 for each DC subpopulation)." (PMID 33919875, 2021). "Multi-color IHC staining also validated the existence of CD11C + LAMP3 + PDL1 + IDO + DCs in tumor tissue." (PMID 33293583, 2020). "The biologic function of LAMP3 in tumor migration and metastasis needs therefore to be further characterized." (PMID 31064137, 2019). "Overexpression of LAMP3 led to evident increased cell proliferation, indicating that LAMP3 is required for cell viability and promotes OS tumor cell growth." (PMID 30008754, 2018). "In univariate analysis, high expression of LAMP3 (P = 0.013), low degree of tumor differentiation (P = 0.018), node metastasis (P < 0.001), and advanced TNM stage (P = 0.001) were markedly related to the overall survival in patients with OSCC." (PMID 28607528, 2017). "In this study, the expression of LAMP3 was compared between cancerous tissues of OSCC and normal oral mucosa, and we found that LAMP3 was highly expressed in tumor cells." (PMID 28607528, 2017). "Chi-square analysis revealed a significantly positive correlation of high expression of LAMP3 with a low degree of tumor differentiation (P = 0.011) and an advanced TNM stage (P = 0.043)." (PMID 28607528, 2017). "In our study, we mainly detected LAMP3 protein expression in epithelial cells, only in rare occasions (<5 cases) did we also observe tumor infiltrating lymphocytes positive for LAMP3 protein." (PMID 25362357, 2014).